BPIFB4 (BPI fold containing family B member 4)
Description:
May have the capacity to recognize and bind specific classes of odorants. May act as a carrier molecule, transporting odorants across the mucus layer to access receptor sites. May serve as a primary defense mechanism by recognizing and removing potentially harmful odorants or pathogenic microorganisms from the mucosa or clearing excess odorant from mucus to enable new odorant stimuli to be received (By similarity).
Synonyms: C20orf186; LPLUNC4; dJ726C3.5; RY2G5
Tractability: Antibody: UniProt places it where antibodies can reach, with medium confidence; UniProt predicts a signal peptide or a membrane-spanning region; its Gene Ontology location is reachable by antibodies, with medium confidence. PROTAC: ubiquitination databases record sites on it.
Gene: Protein-coding gene on chromosome 20 (33,079,643 to 33,111,751, forward strand). Ensembl gene ENSG00000186191.
Subcellular location: Secreted; Cytoplasm
Subcellular location (Human Protein Atlas): Actin filaments; Cytosol; Predicted to be secreted
Pathways (Reactome):
Immune System: Antimicrobial peptides
Gene Ontology:
Molecular function: lipid binding
Cellular component: cytosol; cytoplasm; extracellular region
Genetic constraint (gnomAD): Loss-of-function variants: 62 observed, 70.79 expected, observed/expected ratio (o/e) 0.88, 90% interval 0.71 to 1.08. The upper end of that interval is the gene's LOEUF score, 1.08, which puts it in group 4 of 6, group 1 being the genes least tolerant of losing a copy. Missense variants: 786 observed, 819.72 expected, observed/expected ratio (o/e) 0.96, 90% interval 0.9 to 1.02. Synonymous variants: 329 observed, 344.84 expected, observed/expected ratio (o/e) 0.95, 90% interval 0.87 to 1.04.
Homologues: Orthologues: chimpanzee BPIFB4 (98% identical), macaque BPIFB4 (92% identical), dog BPIFB4 (90% identical), pig BPIFB4 (89% identical), rat Bpifb4 (86% identical), mouse Bpifb4 (86% identical), guinea pig BPIFB4 (82% identical), tropical clawed frog bpifb4 (44% identical), Caenorhabditis elegans C06E8.5 (14% identical). Paralogues in human: BPIFB3 (29% identical), BPIFB6 (22% identical), BPIFB2 (19% identical), BPI (15% identical), LBP (15% identical), BPIFC (15% identical), BPIFB1 (15% identical), CETP (14% identical), PLTP (13% identical), BPIFA1 (9% identical), BPIFA3 (7% identical), BPIFA2 (7% identical).
Diseases named in the same sentence as BPIFB4 in open-access papers:
BPIFB4 is named in the same sentence as 40 diseases in open-access papers, as found by Europe PMC text mining. Sharing a sentence is not in itself a finding about the gene and the disease. The quoted sentences say what the papers report.
atherosclerosis (10 papers, 2020 to 2024). A disease characterized by the build-up of fatty material and calcium deposition in the arterial wall resulting in partial or complete occlusion of the arterial lumen. "In experimental studies, researchers observed that administration of the BPIFB4 protein encoded by the LAV-BPIFB4 gene to the human blood vessels of patients with atherosclerosis resulted in improved vascular activity, reduced blood pressure, and increased resistance to cellular stress." (PMID 36079922, 2022). "LAV of BPIFB4 gene was described to protect from age-related endothelial dysfunction and atherosclerosis, 2 main age-related conditions, mainly by conferring subjects with a favorable maintenance of nitric oxide bioavailability and huge anti-inflammatory profile." (PMID 34396395, 2021). "Moreover, a polymorphic variant of the BPIFB4 gene associated with exceptional longevity (LAV-BPIFB4) confers protection from cardiovascular diseases underpinned by low-grade chronic inflammation, such as atherosclerosis." (PMID 32547549, 2020).
endothelial dysfunction (7 papers, 2017 to 2024). In vascular diseases, endothelial dysfunction is a systemic pathological state of the endothelium (the inner lining of blood vessels) and can be broadly defined as an imbalance between vasodilating and vasoconstricting substances produced by (or acting on) the endothelium. "The Longevity-Associated Variant (LAV) of the human BPIFB4 gene was found to correct endothelial dysfunction, one of the mechanisms underlying frailty, in aging mice whereas the RV-BPIFB4 variant induced opposite effects." (PMID 31461407, 2019). "First of all, we transfected mouse resistance vessels with plasmids encoding the RV or the WT isoform of BPIFB4 to evaluate the impact on vascular function, finding that RV-BPIFB4 impairs eNOS signaling and induces endothelial dysfunction, hallmarks of aging and cardiovascular disease." (PMID 28852218, 2017).
cardiomyopathy (6 papers, 2020 to 2024). A disease of the heart muscle or myocardium proper. "Therefore, additional studies are necessary to determine if BPIFB4 down‐regulation in the human heart contributes to the development of cardiomyopathies, and thereby may represent a useful diagnostic and therapeutic biomarker." (PMID 32384208, 2020).
COVID-19 (5 papers, 2021 to 2024). A disease caused by infection with severe acute respiratory syndrome coronavirus 2. "We have recently described that the bactericidal/permeability-increasing fold-containing family B member 4 (BPIFB4), discovered as both a longevity-associated and a host defense protein with a proved immunomodulatory activity, could represent a novel prognostic determinant in COVID-19." (PMID 35887555, 2022). "Among SARS-CoV-2 patients, we also found more decreased BPIFB4 plasma levels in severe COVID-19 subjects with respect to low-grade patients, asserting that BPIFB4 levels are inversely correlated with disease severity." (PMID 35887555, 2022). "In COVID-19 patients, we recently attributed a new prognostic value to BPIFB4, a natural defensin against dysregulation of the immune responses." (PMID 35887555, 2022). "From a translational point of view, a better characterization of BPIFB4 clinical relevance by investigating its expression in damaged tissues or PBMCs obtained from COVID-19 patients will help to validate BPIFB4 as a valuable biomarker for COVID-19 severity." (PMID 34396395, 2021). "The reduced plasma level of BPIFB4 in COVID-19 patients led us to deeply investigate the putative protective role of BPIFB4 in in vitro studies." (PMID 34396395, 2021). "We examined the plasma BPIFB4 levels in n = 64 patients with COVID-19 (median age 65, range 20–91) consecutively admitted to “San Giovanni di Dio e Ruggi d’Aragona” University Hospital of Salerno." (PMID 34396395, 2021). "Considering all of these findings, BPIFB4 plasma levels might represent a valuable parameter that is able to predict COVID-19 severity in a sex-related manner." (PMID 35887555, 2022). "In this scenario, the aim of our study was to more deeply investigate the protective role of higher levels of BPIFB4 among COVID-19 patients and determine if sex may affect its prognostic value." (PMID 35887555, 2022). "Furthermore, its dual role on immune compartment and in fruitful stress response to limit cellular damage makes BPIFB4 an attractive therapeutic tool to counteract complications of COVID-19." (PMID 34396395, 2021). "BPIFB4 has been shown to serve as a biomarker of healthy aging and previous finding on its prognostic significance in vascular pathology (ie, atherosclerotic patients), prompted us to examine BPIFB4 contribution in COVID-19." (PMID 34396395, 2021). "Thus, the present study was designed to assess the presence and significance of BPIFB4 level in COVID-19 patients and the potential therapeutic use of LAV-BPIFB4 in fighting COVID-19." (PMID 34396395, 2021). "Importantly, BPIFB4 values were significantly lower in SARS-CoV-2-positive individuals as compared with SARS-CoV-2-negative ones (57.31 ± 53.13 pg /mL vs 108.1 ± 66.4 pg /mL, p = .0002) pointing to BPIFB4 as a bona fide biomarker inversely related to COVID-19 diagnosis." (PMID 34396395, 2021). "In contrast, in line with our previous results, BPIFB4 levels were inversely related to the severity of COVID-19 in the male group but not in the female group." (PMID 35887555, 2022). "Indeed the reduced circulating levels of BPIFB4 in patients with severe disease (characterized by elevated levels of CRP and LDH) validate its prognostic significance for severity in patients with COVID-19." (PMID 34396395, 2021). "Since the crucial role of endothelial cells in COVID-19 and the known role of LAV-BPIFB4 in modulating the endothelial function, BPIFB4 might exert its protective effect in endothelium dysfunction occurring during inflammatory conditions also opposing high levels of MCP-1." (PMID 36447743, 2021). "Based on previous studies on the prognostic relevance of BPIFB4 in vascular pathology and its association with the degree of carotid stenosis in atherosclerotic patients, we moved to analyze the plasma BPIFB4 levels in n = 32 severe (high grade) and n = 32 nonsevere (low grade) COVID-19 patients." (PMID 34396395, 2021).
ischemia (4 papers, 2017 to 2024). A hypoperfusion of the BLOOD through an organ or tissue caused by a PATHOLOGIC CONSTRICTION or obstruction of its BLOOD VESSELS, or an absence of BLOOD CIRCULATION. "In this study, we show that the levels of BPIFB4 expression contribute to the heart’s functional state during ischemia." (PMID 37582912, 2023). "We hypothesize that downregulation of BPIFB4 expression marks the severity of coronary artery disease (CAD) in human subjects, and supplementation of the LAV-BPIFB4 protects the heart from ischemia." (PMID 37582912, 2023). "Interestingly, although endogenous Bpifb4 expression was equally induced in all the heart layers, we found that LAV-BPIFB4 protein therapy promoted significant microvascular enhancements only in the subendocardial region, which is the most vulnerable to ischemia." (PMID 39501278, 2024). "BPI-Fold-Containing-Family-B-Member-4 (BPIFB4) protein is higher in healthy vs. non-healthy (frail) LLIs serum and its longevity-associated variant forced expression improves cardiovascular outcomes in ischemia mice models." (PMID 28121621, 2017).
diabetes (3 papers, 2020 to 2023). "Long-living individuals are protected from the adverse influence of diabetes on the heart, and the transfer of a longevity-associated variant (LAV) of the human BPIFB4 gene protects cardiac function in the db/db mouse model." (PMID 32455800, 2020).
type 2 diabetes (3 papers, 2020 to 2024). "In previous studies, a single administration of the longevity-associated variant (LAV) of the human BPIFB4 gene halted heart decline in older and type 2 diabetic mice." (PMID 39501278, 2024).
acute myocardial infarction (2 papers, 2023 to 2024). Necrosis of the myocardium, as a result of interruption of the blood supply to the area. "In the present study, we assessed the association of BPIFB4 expression and CAD severity in a cohort of patients with acute myocardial infarction (MI)." (PMID 37582912, 2023).
age (1 paper, 2022). A temporal measurement of the time period elapsed since an identifiable point in the life cycle of an organism. "The longevity-associated variant (LAV) of the bactericidal/permeability-increasing fold-containing family B member 4 (BPIFB4) gene previously demonstrated a modulatory activity in restoring age-related immune dysfunction and in balancing the low-grade inflammatory status of elderly people." (PMID 35053408, 2022).
anemia (1 paper, 2023). A reduction in the number of red blood cells, the amount of hemoglobin, and/or the volume of packed red blood cells. "Unfortunately, there is insufficient information to understand the direct involvement of BPIFB4 in non-regenerative anemia, and its association with the pathogenesis of PIMA remains unknown." (PMID 37146011, 2023).
brain tumor (1 paper, 2021). "This suggests that BPIFB4 marks a population of brain tumor–initiating cells endowed with the ability to escape standard therapy to drive recurrence, as described in the classical CSC hypothesis." (PMID 34878832, 2021).
breast carcinoma (1 paper, 2025). "In our study, knockout of Stk11 in murine breast cancer cell lines resulted in significant enrichment of cytoskeleton-related gene (Bpifb4), and cell adhesion/migration-related genes (Cdh5, Plat, and Pmp22), along with enhanced tumorigenicity in vivo." (PMID 41051525, 2025).
heart failure (1 paper, 2023). Inability of the heart to pump blood at an adequate rate to meet tissue metabolic requirements. "Conversely, BPIFB4 silencing in normal pericytes mimed the heart failure pericytes." (PMID 36635236, 2023).
megakaryoblastic leukemia (1 paper, 2024). "Consistently, we also found BPIFB4 to be highly expressed in megakaryoblastic leukemia MEG-01 cells." (PMID 38884925, 2024).
infection (7 papers, 2017 to 2023). The state of being infected such as from the introduction of a foreign agent such as serum, vaccine, antigenic substance or organism. "To further validate the role of BPIFB4, whose level was found decreased in course of infection, we finally investigated its activity in cell damage of SARS-CoV-2 lysate against a panel of susceptible cell lines in vitro." (PMID 34396395, 2021). "At functional level, a recovery of the BPIFB4 secretory profile and a better response to the inhibition of the proteasome were observed following infection with LAV-BPIFB4." (PMID 32683420, 2020). "Specifically, a main nuclear distribution of BPIFB4 was acquired in response to LAV-BPIFB4 infection in STHdh Q111/111." (PMID 32683420, 2020). "Importantly, the observed ΥH2AX induction was drastically blunted in response to BPIFB4 isoform infection." (PMID 36499641, 2022).
cardiovascular diseases (6 papers, 2017 to 2024). "These advantages could be transferred through BPIFB4 gene therapy to animal models of cardiovascular disease." (PMID 39501278, 2024). "Exceptionally high circulating levels of BPIFB4 have been found in long-living individuals, the successful aging model by definition, demonstrating BPIFB4 could be involved in a heightened response against age-related and cardiovascular diseases." (PMID 35887555, 2022). "Mechanistic investigations elucidated the signal transduction pathways by which BPIFB4 protein, and its LAV-isoform induces pleiotropic effects on immune system or in presence of cardiovascular disease to offer protection from age-related impairment." (PMID 36447743, 2021).
neoplasm (2 papers, 2021 to 2022). A benign or malignant tissue growth resulting from uncontrolled cell proliferation. "In all three recurrent MB lines (D425-Re, HD-MB03-Re, and SU_MB002), reduced BPIFB4 expression translated into a reduced tumor burden in both brains and spines and prolonged survival." (PMID 34878832, 2021).
bacterial infection (1 paper, 2022). "The BPIFB6, BPIFB4, BPIFB2, and BPIFB3 genes are the most significant because they are involved in biological signaling pathways, which play an essential role in innate immunity against bacterial infection." (PMID 36672756, 2022). "The BPIFB6, BPIFB4, BPIFB2, and BPIFB3 genes were the most significant because they are involved in biological signaling pathways, which play an essential role in innate immunity against bacterial infection." (PMID 36672756, 2022).
heart disease (1 paper, 2023). "The present study provides compelling evidence for the protective role of BPIFB4 and its longevity-associated variant against heart disease." (PMID 37582912, 2023).
BPIFB4 also shares sentences with these, for which no sentence is quoted: Hypertension (6 papers); diabetic cardiomyopathy (4); cancer (2); glioblastoma (2); Huntington disease (2); R6 (2); acute coronary syndrome (1); cardiac ischemia (1); coronary artery disease (1); fibrosis (1); glioma (1); immune dysfunction (1); inflammatory bowel disease (1); limb ischemia (1); melanoma (1); mucormycosis (1); Myocardial fibrosis (1); neurodegenerative disease (1); Sepsis (1); Thrombocytopenia (1); virus infection (1).